ENSG00000252438
Gene: Small nucleolar RNA gene on chromosome 10 (12,415,928 to 12,416,000, forward strand). Ensembl gene ENSG00000252438.
Homologues: Orthologues: mouse Snord45c (79% identical), rat Snord45c (78% identical). Paralogues in human: SNORD45C (84% identical), SNORD45A (73% identical), SNORD45B (64% identical).